HGF (hepatocyte growth factor)
Diseases named in the same sentence as HGF in open-access papers (continued):
Sharing a sentence is not in itself a finding about the gene and the disease.
ovarian carcinoma (continued). "Elevated serum levels of hepatocyte growth factor (HGF) and high tumor expression of c-Met are both indicators of poor overall survival from ovarian cancer (OVCA)." (PMID 23467907, 2013). "Hepatocyte growth factor present in malignant ascites of ovarian cancer patients has been shown to stimulate the migration of ovarian cancer cells." (PMID 24093089, 2013). "Next, we will discuss the HGF/MET axis alterations in ovarian cancer and its clinical implication, as well as the potential therapeutic use of HGF/MET inhibitors in ovarian cancer." (PMID 23320251, 2012). "In a series of studies, it has been shown that HGF triggers survival signaling pathways in ovarian cancer cells, but this survival effect is overwhelmed by the dominant role of the apoptotic effect of p38 MAPK on the treated cells." (PMID 23320251, 2012). "In this paper, we will discuss the HGF/MET pathway in ovarian cancer, its clinical significance, and its potential use as a target therapy in the future." (PMID 23320251, 2012). "HGF was highly expressed in ovarian cancer peritoneal ascites and in benign ovarian and cancer cysts fluid." (PMID 23320251, 2012). "We therefore tested the effectiveness of lower decreasing concentrations of recombinant HGF and found that a level as low as 1.25 ng/ml of HGF was able to sensitise ovarian cancer cells to cisplatin." (PMID 22999213, 2012). "We then test HGF effectiveness in sensitising ovarian cancer cell lines to chemotherapeutics at the plasma concentrations obtained in patients following nadroparin administration." (PMID 22999213, 2012). "The HGF concentrations measured after both acute and chronic treatment were found to be effective in sensitising ovarian cancer cells to chemotherapeutics." (PMID 22999213, 2012). "HGF/MET pathway plays a major role in ovarian cancer onset and progression including invasiveness and metastasis." (PMID 23320251, 2012). "Subsequently, the biological activity of the measured HGF serum levels was tested in assays of ovarian cancer cell sensitization to drugs." (PMID 22999213, 2012). "We studied gynaecological patients with the intent of exploiting the ability of HGF to sensitise ovarian cancer cells to chemotherapeutic effects." (PMID 22999213, 2012). "Few compounds have been explored in ovarian cancer such as NK4: NK4 is a HGF/SF fragment that competes with HGF/SF for binding to c-Met receptor in ovarian cancer cell lines." (PMID 23320251, 2012). "We demonstrate here that HGF concentrations as low as those obtained after nadroparin injection are effective in sensitising ovarian cancer cells to chemotherapeutics." (PMID 22999213, 2012). "Deregulated HGF/C-met signaling has been observed in many tumors, including ovarian carcinoma, and been proved to contribute to tumor dissemination and metastasis." (PMID 21923915, 2011). "The MET receptor tyrosine kinase and its ligand (hepatocyte growth factor, HGF) are highly expressed in ovarian cancers, and MET inactivation by small molecular inhibitor and siRNA reduced tumor burden and metastasis in nude mice with ovarian cancer." (PMID 21962244, 2011). "Peritoneal dissemination is critical for the progression of ovarian cancer, and our study revealed that HGF induces migration and invasion of ovarian cancer cells." (PMID 10732763, 2000). "In advanced ovarian cancer, HGF in serum was demonstrated as an indicator of poor prognosis." (PMID 37828456, 2023). "HGF derived from CAFs promote ovarian cancer cell proliferation through the activation of the PI3K/Akt signaling pathway, favoring cell proliferation and survival, and the upregulation of GRP78, an endoplasmic reticulum chaperone involved in protein folding that plays a role in drug resistance." (PMID 35574025, 2022).
ovarian carcinoma (continued). "Although few patients with ovarian cancer were included in the phase I clinical trial of a drug targeting HGF/c-MET, the phase II clinical trial of rilotumumab in patients with recurrent epithelial ovarian, fallopian tube, or primary peritoneal carcinoma demonstrated a significant effect." (PMID 35630066, 2022). "The actions of HGF are mediated through the c-Met receptor, found on ovarian cancer cells." (PMID 35574025, 2022). "In addition, high levels of HGF are found in malignant ascites of patients with ovarian cancer, which promotes cancer cell migration by activating c-MET." (PMID 35630066, 2022). "On the other hand, the concerted regulation of miR-199a-3p by shear stress and HGF may explain the emergence of chemoresistant tumors in the late stages of ovarian cancer." (PMID 35676254, 2022). "Therefore, the HGF/c-MET signal has been used as a therapeutic target in ovarian cancer clinical trials." (PMID 35874635, 2022). "Moreover, HGF is present at high concentrations in malignant ascites of ovarian cancer patients and induces migration of human peritoneal mesothelial cells by activation of cMET." (PMID 33738970, 2021). "Considering the already confirmed protumorigenic role of the HGF/cMET pathway in ovarian cancer, there might be a biologically relevant interaction between HGF/cMET signaling and micrometastasis dynamics." (PMID 33738970, 2021). "In ovarian cancer, the HGF/cMET pathway is aberrantly activated." (PMID 33738970, 2021). "Consequently, HGF/cMET signaling has been exploited as a therapeutic target in clinical trials on ovarian cancer." (PMID 33738970, 2021). "In ovarian cancer, HGF could increase the proliferation, migration and tube-like structure formation in microvascular endothelial cells." (PMID 32967712, 2020). "PARP1 is shown to impact invasion of ovarian cancer cells stimulated by HGF." (PMID 33133138, 2020). "In ovarian cancer, CAFs promote cancer cell proliferation by excessive secretion of hepatocyte growth factor (HGF), through the activation of cMet/PI3K/Akt pathways and glucose-regulated protein 78 (GRP78) that promote chemoresistance, cancer cell invasion and cell migration." (PMID 31323899, 2019). "Migration and invasion assays were performed to determine whether HGF affects the movement of ovarian cancer cells." (PMID 31355133, 2019). "Hepatocyte growth factor (HGF) is important in ovarian cancer cell migration and invasion." (PMID 31355133, 2019). "In addition, hepatocyte growth factor (HGF) down-regulates E-cadherin, beta-catenin, and caveolin-1, disassembly of cell-cell contacts, and invasion and migration enhancement in human ovarian cancer cells." (PMID 31759347, 2019). "Moreover, HGF concentrations were shown to be elevated in the ascitic fluid of ovarian cancer patients, suggesting that HGF enhances ovarian cancer cell migration and peritoneal dissemination." (PMID 31355133, 2019). "Moreover, activation of p70S6K1 in human ovarian carcinoma cells in response to stimulation by hepatocyte growth factor (HGF) also led to increased expression of matrix metalloproteinase 9 (MMP9) and higher migration rate of these cells." (PMID 30705751, 2018). "CAFs from ovarian cancer patients secrete high levels of hepatocyte growth factor (HGF) that promotes cancer cell proliferation, chemoresistance, invasion, and migration though constitutive activation of cMet/PI3K/Akt pathways and glucose-regulated protein 78 (GRP78)." (PMID 30042343, 2018). "In summary, HGF/c-Met axis is a new therapeutic target for ovarian cancer." (PMID 28258248, 2017). "However, we found that CAF-derived HGF was the crucial contributor to stimulate cell growth and drug resistance in ovarian cancer." (PMID 28258248, 2017). "The upregulation of FER in ovarian cancers could trigger a signaling cascade downstream of c-Met in a HGF independent manner." (PMID 28212658, 2017).
ovarian carcinoma (continued). "Furthermore, HGF increased the levels of c-Met and promoted cell proliferation and drug resistance in ovarian cancer cells, consistent with the previous studies." (PMID 28258248, 2017). "As in vitro motility and invasiveness was strongly activated by HGF, a circulating growth factor that is considered a poor prognostic marker in ovarian cancer patients, control and silenced cells were further engineered to secrete HGF in order to enhance their metastatic potential." (PMID 26625210, 2016). "In addition to comparing baseline variation between the cell lines, we determined how these behaviors changed in response to four growth factors implicated in ovarian cancer progression: HB-EGF, NRG1β, IGF1, and HGF." (PMID 26648788, 2015). "Similarly, a high level of HGF in serum is an indicator of ovarian cancer in women presenting with a pelvic mass, and predictive of poor prognosis in women with advanced epithelial ovarian cancer." (PMID 26138303, 2015). "We and others have shown that Met tyrosine kinase, a high affinity receptor for HGF, is often overexpressed in ovarian carcinomas and cancer cell lines, and constitutive activation of the Met receptor through paracrine/autocrine mechanisms has been observed with progressive neoplastic changes." (PMID 25193855, 2014). "The findings reported here are important also when approaching tumour therapy from the perspective of inhibiting HGF and MET, HGF is a Janus-faced molecule, which sensitizes ovarian cancer cells to chemotherapeutics, but is alone able to trigger cancer cell growth and invasiveness." (PMID 22999213, 2012). "Therefore, it would make sense to evaluate the effect of HGF on ovarian cancer cell response to paclitaxel and cisplatin." (PMID 23320251, 2012). "The HGF/MET signaling pathway is abnormal in numerous cancers including ovarian cancer." (PMID 23320251, 2012). "However, one thing remained certain, that the involvement of HGF/MET pathway in promoting cell proliferation and dissemination in ovarian cancer was highly associated with the expression of high levels of the HGF receptor." (PMID 23320251, 2012). "This unexpected result led the authors to suggest that HGF may be used to improve the response to chemotherapy in human ovarian carcinoma over-expressing c-Met." (PMID 23320251, 2012). "Moreover, infection of ovarian cancer cells with Ras dominant-negative adenovirus reduced the HGF-induced motogenic and invasive activities." (PMID 10732763, 2000). "Additionally, both MEK and PI3-kinase pathways downstream of Ras were involved in HGF-stimulated ovarian cancer cell invasiveness." (PMID 10732763, 2000). "However, adding HGF, which induces MET phosphorylation, overcame the inhibition of an ovarian cancer cell invasion caused by α5β1 blocking antibodies or siRNA, indicating that integrins act upstream of MET in an HGF-independent manner, playing a crucial role in MET activation." (PMID 39769452, 2024). "In this scenario, the cancerous tissue itself may contribute to an elevated sHGF level in blood, which is supported by previous studies showing that (a) HGF is present in malignant ascites and that (b) HGF expression in ovarian cancer tissue parallels (increasing) tumor stage." (PMID 33738970, 2021). "Furthermore, it was proposed that circulating serum HGF (sHGF) levels are significantly raised in ovarian cancer patients at primary diagnosis compared with patients with borderline tumors or benign disease, and that elevated sHGF levels indicate poor prognosis." (PMID 33738970, 2021). "Whether HGF can induce CD44 expression in ovarian cancer cells needs further study." (PMID 32967712, 2020). "Specific neutralizing antibodies directed against four agents known from the literature to cause EMT—that is, EGF, HGF, IGF-1, and TGF-β1—were added to the malignant ascites to establish whether some of these agents may be responsible for EMT development in ovarian cancer cells." (PMID 30609691, 2019).
ovarian carcinoma (continued). "Thus, indicating that while the paracrine interaction of HGF/MET is important in normal ovarian physiology, the autocrine HGF/MET loop seems to be important in ovarian cancer onset and maybe progression." (PMID 23320251, 2012). "Finally, we evaluated whether the HGF concentrations measured in our patients after nadroparin administration were effective in sensitising ovarian cancer cells to chemotherapeutics." (PMID 22999213, 2012). "Therefore, we presumed that inhibition of MACC1 by RNAi might suppress the malignant behavior of ovarian carcinoma cells via HGF/Met and MEK/ERK pathways, at least in part." (PMID 21923915, 2011). "The observed cell migration was blocked by c-MET inhibition, suggesting that HGF/c-MET signaling mediates cell migration in endometriosis and ovarian cancer." (PMID 40076450, 2025). "HGF and VEGF-A are present in the O-ASC CM of ovarian cancer and endometriosis, albeit at variable levels." (PMID 40076450, 2025). "Second, the omenta of HGSC patients produced higher levels of three cytokines, namely HGF, SDF-1a/CXCL12 and MCP-1/CCL2, known to mediate cell migration, invasion, proliferation and metastasis in ovarian cancer." (PMID 40076450, 2025). "The level of HGF produced by the omentum of endometriosis patients was similar to that in CCC, EC and MC subtypes of ovarian cancer." (PMID 40076450, 2025). "HGF, c-MET and PTTG1 are potential therapeutic targets for inhibiting the abdomen–pelvic/peritoneal spread of endometriosis and ovarian cancer." (PMID 40076450, 2025). "The HGF treatment has been shown to increase the cell growth of KGN and HO8910 ovarian cancer cell lines and the PC-3 cell line." (PMID 35204839, 2022). "In the preclinical model of ovarian cancer, YYB-101 blocked HGF, leading to the inhibition of the progression of ovarian cancer cells through downstream signaling of the c-MET axis." (PMID 35630066, 2022). "CAF-derived HGF promotes cell proliferation and drug resistance by upregulating the c-Met/PI3K/Akt and GRP78 signalling pathways in ovarian cancer cells." (PMID 36105798, 2022). "Again, however, the way in which the reduction in HGF and UACA correlate with the cisplatin resistance of ovarian cancer needs further investigation." (PMID 35008958, 2022). "HGF has been reported to reduce the expression of E-cadherin, β-catenin, and caveolin-1 in HO8910 ovarian cancer cell line in vitro." (PMID 35565396, 2022). "On the other hand, actin cytoskeletal rearrangement in ovarian cancer is regulated by kinases such as p70S6, the downstream effector of the phosphatidylinositol 3-kinase/Akt (PI3K/Akt) pathway activated by HGF." (PMID 35630066, 2022). "Co-treatment of shear stress and HGF resulted in upregulation of ALDH3 and ovarian cancer stemness marker CD44, which was abrogated in the presence of miR-199a-3p overexpression." (PMID 35676254, 2022). "We examined the effects of hepatocyte growth factor (HGF), epidermal growth factor (EGF), and tumor necrosis factor alpha (TNFα), which are particularly relevant to the progression of ovarian cancer." (PMID 35676254, 2022). "We present the findings of clinical studies using small chemicals or antibodies targeting HGF/c-MET signaling in various cancer types, particularly in ovarian cancer." (PMID 35630066, 2022). "The hepatocyte growth factor (HGF) has been known to play a predominant role in many types of human cancers, promoting invasiveness and metastasis of ovarian cancer cultured cells." (PMID 33807612, 2021). "Hepatocyte growth factor (HGF) released by CAF promotes proliferation and chemotherapy resistance of ovarian cancer (OC) cells by regulating the c-Met/ phosphatidylinositol 3-kinase (PI3K) /Akt and glucose related protein 78(GRP78) signaling pathways." (PMID 33819917, 2021). "In lung and ovarian cancers, CAF-derived HGF activates PI3K/Akt signaling and suppresses the paclitaxel-induced apoptosis of cancer cells." (PMID 33050576, 2020).
ovarian carcinoma (continued). "It is very plausible that this effect was associated with the higher secretion levels of several agents known to support ovarian cancer cell progression by these cells, such as CCL2, CXCL8, CXCL12, ICAM-1, IL-6, HGF, PAI-1, uPA, TGF-β1, and VEGF." (PMID 31086083, 2019). "In conclusion, the present study demonstrated that HGF was blocked by YYB-101, inhibiting the growth of ovarian cancer cells through the signaling pathway mediated by c-MET, the target receptor for HGF." (PMID 31355133, 2019). "In summary, we have demonstrated herein tumour microenvironment, in particular CAF-derived HGF, contributed to cell proliferation and drug resistance via activating c-Met/PI3K/Akt and GRP78 signalling in ovarian cancer cells." (PMID 28258248, 2017). "In the present study, we demonstrated for the first time that HGF in the tumour microenvironment promoted cell proliferation though activating PI3K/Akt and GRP78 signalling in ovarian cancer cells." (PMID 28258248, 2017). "In this report we show that senescent human peritoneal mesothelial cells (HPMCs) alter the secretory profile of ovarian cancer cells (A2780, OVCAR-3, SKOV-3) by increasing the release of four angiogenic agents: CXCL1, CXCL8, HGF, and VEGF." (PMID 26433963, 2016). "High levels of hepatocyte growth factor (HGF) and its tyrosine kinase receptor (cMET) are found in malignant ovarian cysts and ascitic fluid from women with ovarian carcinomas." (PMID 26356073, 2015). "To address the ability of HGF and INC280 to affect the ability of ovarian cancer cells to adhere to peritoneum, we performed ex vivo adhesion assays using vital tissue removed from mouse peritoneum." (PMID 26138303, 2015). "Furthermore, elevated HGF serum levels could predict poor prognosis in advanced ovarian cancers." (PMID 26100469, 2015). "It has been also shown that hepatocyte growth factor (HGF) and its receptor MET are significantly increased in ovarian cancer patients who relapse shortly after chemotherapy." (PMID 25888626, 2015). "HGF downregulates TSP-1 via the (microtubule affinity-regulating kinase) MARK signaling pathway, leading to ovarian cancer cell invasion." (PMID 23749112, 2013). "Once again, these results data indicate that HGF/MET overexpression has a significant role in promoting cell migration and matrix degradation and therefore ovarian cancer progression." (PMID 23320251, 2012). "Hepatocyte Growth Factor (HGF) enhances cytotoxicity of paclitaxel (PTX) and cisplatin (CDDP) in human ovarian cancer cells." (PMID 22999213, 2012). "Several studies confirmed the important role of HGF/MET signaling in the transformation of surface ovarian epithelial cells and in the growth and dissemination of ovarian cancer." (PMID 21962244, 2011). "It is likely that, similar to other ovarian cancer cells like SKOV3, fully transformed and peritoneal metastatic FTE cells have established autocrine signaling pathways involving receptor tyrosine kinase signals such as HGF/cMET." (PMID 41511363, 2026). "We also discuss that HGF/c-MET-targeted therapy, when combined with chemo drugs, could be an effective strategy for ovarian cancer therapeutics." (PMID 35630066, 2022). "When HGF/c-MET-targeted molecules were applied to ovarian cancer in various clinical trials, no specific therapeutic efficacy was observed." (PMID 35630066, 2022). "In this review, we explain the properties of the hepatocyte growth factor (HGF)/mesenchymal-epithelial transition factor (c-MET) and how the signaling pathway of HGF/c-MET is activated in different cancers and involved in tumorigenesis and metastasis of ovarian cancer." (PMID 35630066, 2022). "We have utilized an ex vivo assay to demonstrate that in the presence of HGF, INC280 acts to decrease cellular peritoneal adhesion, and thus may be useful in decreasing metastasis in ovarian cancer post-surgery." (PMID 26138303, 2015).